SMAD3 (SMAD family member 3)
Diseases named in the same sentence as SMAD3 in open-access papers (continued):
Sharing a sentence is not in itself a finding about the gene and the disease.
tumor (continued). "In this way, Smad3 could outcompete Smad2 for preferentially gaining a tumor-promoting function." (PMID 35794621, 2022). "Although these authors did not assess DTC dormancy in their model, they could attribute the growth differences observed were due in part to differential regulation of angiogenic factors, whereby activity of SMAD3 seemed to promote VEGF production in tumor cells while SMAD2 inhibited it." (PMID 33805598, 2021). "Moreover, TGF-β1 promotes survival of post-thymic naïve CD4+ T lymphocytes to later promote CD4+CD25+ Treg differentiation from uncommitted peripheral CD4+ cells via FOXP3 and Smad3, while preventing its differentiation into the Th-1 and Th-2 effector cell, thereby leading to tumor cell tolerance." (PMID 34299192, 2021). "Besides, TGF-β1 could enhance PD-1 expression on TILs (tumor infiltrating lymphocytes) through Smad3, thereby inducing tumor escape from host immune responses." (PMID 34326692, 2021). "Hence, SMAD3 could be a further druggable target and SMAD3 blocking by pharmacological strategies could represent an additional promising approach to improve the tumor radiosensitivity." (PMID 35002714, 2021). "Interestingly, we recovered the tumor‐promoting genes SMAD3, BIRC3, and SLC9A5 identified above." (PMID 33724679, 2021). "For the first time, we demonstrated that the combination of SMAD3 tumor expression level with host SMAD3-rs745103 genotype could identify smaller groups of patients at significantly higher risk of not responding to nCRT treatment compared to individual molecular parameters." (PMID 35002714, 2021). "In vivo, resveratrol enhanced tumor growth inhibition and reduced body weight loss and kidney function impairment by cisplatin in MDA231 xenografts, and significantly reduced the expressions of P-AKT, P-PI3K, Smad2, Smad3, P-JNK, P-ERK, and NF-κB in tumor tissues (p < 0.05)." (PMID 33921192, 2021). "In addition, SMAD3 can act as a target of multiple miRNAs to regulate tumor progression." (PMID 32774166, 2020). "In addition, miR‐133a mimic suppressed tumor growth by modulating the TGF‐β/Smad3 pathway in vivo." (PMID 33074595, 2020). "Hence, when acting as a signal transducer of TGF-β, SMAD3 clearly has a tumor-promoting role." (PMID 31817656, 2019). "This may be because of reduced SMAD3 expression in primary tumor cells exposed to hypoxia." (PMID 29991801, 2018). "To this end, we found that the activation of NK cells by either tumor stimuli or cytokines in the presence of TGFβ induces potent NK cell anti-tumor IFNγ and TNFα secretion and alterations in NK cell cytotoxicity, corresponding to the downregulation of T-bet and SMAD3 expression." (PMID 30400618, 2018). "Furthermore, studies have suggested that knockdown of SMAD3 expression could reduce the growth and metastasis of intraperitoneal tumor in mice via blocking TGF-β/Smad pathway in MMT." (PMID 30154401, 2018). "Thus, it possible that SMAD3 is also affected by M7824, as has been seen in human tumor cell lines." (PMID 29721396, 2018). "Furthermore, the tumour-suppressive function of SMAD3 is sensitive to ECM stiffness." (PMID 30318519, 2018). "Therefore, inhibition of angiogenesis and tumour-invasive activities may account for the additional anticancer mechanism by disrupting Smad3 in the tumour microenvironments." (PMID 28262747, 2017). "Moreover, a marked reduction in vascular endothelial growth factor (VEGF) expression, CD31+ blood vessels, CD4+ Foxp3+ Treg cells and the expression of MMP-2, MMP-9, MMP-13 and C-X-C motif chemokine receptor 4 (CXCR4) in the tumour stroma were observed in the Smad3−/− tumour microenvironment." (PMID 28262747, 2017).
tumor (continued). "In addition, this compound also induces changes on nuclear deoxyribonucleoside triphosphate, and inhibits the proliferation of tumor cells by activating the TGF-β/Smad3 signaling pathway as well as proteins involved in cell proliferation and differentiation and by inducing cell cycle arrest." (PMID 28855870, 2017). "Therefore, deletion of Smad3 may enhance NK cell development in bone marrow and augmentation of host anticancer immunity at the distant tumour microenvironment." (PMID 28262747, 2017). "Most importantly, our results showed that this interaction was dramatically disrupted by transfection of miR-1 mimics, which may be largely attributed to reduction of HIF-1α expression by miR-1 mimics, leading to decrease phosphorylation of Smad3 and inhibit tumor glycolysis." (PMID 28471448, 2017). "Therefore, targeting Smad3-dependent tumour microenvironment may represent a novel and effective anticancer therapy." (PMID 28262747, 2017). "Given that deficiency of Smad3 prevents TGF-β1-mediated inhibition of E4BP4 expression, targeting the TGF-β1/Smad3–E4BP4 axis to accelerate the development of NK cells may enhance their anticancer immunity within the tumour microenvironment." (PMID 28262747, 2017). "Halofuginone in vitro reduced Smad3 protein, inhibited TGFβ-dependent Smad3 phosphorylation and elevated expression of the inhibitory Smad7 in a variety of cell types, such as fibroblasts, hepatic (HSCs) and pancreatic (PSCs) stellate cells, tumor cells, and myoblasts." (PMID 25569515, 2015). "However, the molecular mechanisms underlying how Smad3 signaling shifts from tumor-suppression to oncogenesis have not been well characterized." (PMID 25714018, 2015). "POGLUT1 overexpression was observed to decrease the phosphorylation of Smad3 and the expression of p16 was found to decrease to a level even lower than the background level, as the normal negative feedback regulation mechanism is already impaired in tumor cells." (PMID 25009645, 2014). "Accordingly, in this study, we examined the expression of TGF-β1, Smad2, phospho-Smad2 (p-Smad2), Smad3, phospho-Smad3 (p-Smad3), Smad4, and Smad7 in normal anterior pituitaries, invasive NFPAs, and noninvasive NFPAs and evaluated whether they were correlated with tumor development and invasion." (PMID 24636138, 2014). "Interestingly, we found that knockdown of either TβRII or Smad4 attenuated TGF-β-induced nuclear accumulation of p-Smad3L suggesting that the tumor-promoting activity of autocrine TGF-β is likely mediated in part by its stimulation of linker region phosphorylation of Smad3." (PMID 23704908, 2013). "Smad3–4 may form a transcriptional repressor complex with Snail that mediate EMT in tumours." (PMID 22384029, 2012). "Interestingly, we could still demonstrate, although reduced, Smad3 expression in the tumours, and hence the effects appeared to be synergistic." (PMID 21063400, 2011). "However, both repressive and promotive role in carcinogenesis have been documented for Smad3, thus Smad3 might play a dual role in tumor development dependent on the context of tumor type and its effect on tumor microenvironment." (PMID 22204491, 2011). "Moreover, we have previously shown that core protein extracted from HCV/HCC tumor tissue could bind Smad3 in GST-pull down analyses suggesting that perturbation of TGF-β signaling may also be modulated in vivo." (PMID 19190755, 2009). "One such transcriptional cofactor, the adaptor protein embryonic liver fodrin (ELF) or β2-spectrin (β2SP), is prominently involved in tumor-suppressor functions and cell fate decisions downstream of TGF-β/Smad3 signaling." (PMID 41109667, 2026). "In vivo studies showed that TGF-β1 knockdown significantly inhibited tumor growth, and this effect was achieved by upregulating BRCA1 expression and Smad3 phosphorylation." (PMID 40138287, 2025). "Our findings unveil Smad3 as a critical regulator of MDSC fate and propose novel therapeutic targets for tumor immunotherapy." (PMID 41360769, 2025).
tumor (continued). "By interacting directly with NSCLC cell Smad family members (Smad2, Smad3, and Smad4), MELK inhibits EMT and increases tumor cell motility, invasion, and metastasis." (PMID 40925573, 2025). "Our findings reveal a novel mechanism by which the microbial metabolite ammonia disrupts tumor-suppressive TGF-β signaling via structural and functional modification of SMAD3 adaptor SPTBN1." (PMID 40311681, 2025). "Consistently, m6A levels in Smad3 mRNA were significantly reduced following Mettl3 knockdown in tumor MO-MDSC, accompanied by a notable elevation in Smad3 transcription levels, while Mettl3 overexpression decreased Smad3 expression." (PMID 41360769, 2025). "Strikingly, Mettl3-mediated m6A modification destabilized Smad3 mRNA via Ythdf2-dependent recognition of a specific m6A site (position 4591) in the 3’UTR, accounting for impaired tumor MDSC maturation." (PMID 41360769, 2025). "Our findings reveal that calycosin exerts its anticancer effects by acting on SMAD3 through the NOTCH signaling pathway in monocytes/macrophages, highlighting the intricate interplay between tumor cells and the immune microenvironment in LUAD pathogenesis." (PMID 40361382, 2025). "In the case of SED, 225 TFs were analyzed, with TFBSs of 10 TFs identified as enriched in tumor-specific domains (T-SED), including TP63, SMAD3, JUND, and FOSL1/2." (PMID 41323280, 2025). "Epithelial-mesenchymal transition (EMT) and TGF-β/Smad3 signaling axis dysregulation constitute critical drivers of CDK4/6 inhibitor resistance, enabling tumor cell plasticity and therapeutic evasion." (PMID 40421216, 2025). "Another important factor in tumor metastasis is SMAD3, which, as a key protein molecule in the transforming growth factor-β (TGF-β) signaling pathway, plays a critical regulatory role in tumor metastasis." (PMID 40066091, 2025). "Specifically, the upregulation of SMAD1, SMAD3, SMAD4, BMP2, MAPK1, and SKIL—driven by promoter hypomethylation and reduced expression of tumor-suppressive microRNAs—leads to enhanced activation of both canonical and non-canonical branches of TGF-β signaling." (PMID 40869118, 2025). "Our results demonstrated that NSUN5 KO significantly decreased intracellular SMAD3 and p‐SMAD3 levels, reversing EMT in tumor cells and significantly reducing HCC invasion and metastasis both in vitro and in vivo." (PMID 39531371, 2025). "These CDK inhibitors upregulate CX3CR1 expression via SMAD3 signaling, thereby promoting Mo-MDSC infiltration into tumors and facilitating immune evasion and tumor progression." (PMID 41316412, 2025). "The mouse and human data suggest that SPTBN1 and SMAD3 play critical roles not only in TGF-β signaling but also in mediating the inflammatory and tumor-promoting effects of a dysregulated gut microbiome." (PMID 40311681, 2025). "Our study reveals that calycosin disrupts this process by targeting SMAD3 and modulating NOTCH signaling in monocytes/macrophages, thereby inhibiting tumor-supportive functions and reversing the immunosuppressive TME." (PMID 40361382, 2025). "SIS3 reduced tumor invasiveness by inhibiting the Smad3 signaling pathway, enabling SPNST to effectively target hypoxic tumors and inhibit tumor metastasis." (PMID 39816693, 2025). "To directly test the effect of Smad3 on MO-MDSC maturation, we overexpressed Smad3 in tumor-derived highly immunosuppressive MO-MDSC via lentiviral transduction." (PMID 41360769, 2025). "The TGF-β/SMAD pathway, initiated by TGFB1, activates SMAD3, promoting ECM generation and remodeling, which facilitates tumor metastasis." (PMID 40989695, 2025). "Several tumor-specific TFs were detected within the ED and SED, including TP63, FOSL1, JUND, GRHL2, SNAI2, KLF5, TP73, and SMAD3." (PMID 41323280, 2025). "In a MΦ differentiation system driven by M-CSF from tumor MO-MDSC where approximately 50% of cells transformed, Smad3 levels significantly increased during maturation." (PMID 41360769, 2025).
tumor (continued). "Calycosin was shown to target SMAD3, modulating the NOTCH signaling pathway in monocytes/macrophages and disrupting the tumor immune microenvironment." (PMID 40361382, 2025). "For example, miR-32-5p inhibits migration and invasion in non-small cell lung cancer (NSCLC) by targeting SMAD3 and modulating the TGF-β/SMAD signalling pathway, which is crucial for tumour progression and immune regulation." (PMID 41562703, 2025). "Given the difficulty of driving tumor MO-MDSC into DC in vitro, we determined the role of Smad3 in BM-MO-MDSC maturation into DC." (PMID 41360769, 2025). "Subsequently, MMA has also been confirmed in vivo to increase the expression of INHBA, Ki-67, p-Smad2, p-Smad3, and EMT markers, according to immunohistochemistry, immunofluorescence, and western blotting assays of subcutaneous tumor tissues." (PMID 38252148, 2024). "In comparison with Smad3 wild-type NK cell therapy, the accumulation of DC in LLC tumor was increased twofold by Smad3 knockout NK cell therapy." (PMID 38878186, 2024). "Half of driver gene SVs were deletions, most frequently affecting tumour suppressor genes including RUNX1 (n = 38), PTEN (n = 33) and SMAD3 (n = 30)." (PMID 39112715, 2024). "There results indicated that domperidone inhibited tumor growth by suppressing MEK/ERK and CDK4/SMAD3 pathways via targeting MEK1/2 and CDK4." (PMID 38528618, 2024). "Gradient RMF exposure significantly inhibited tumor growth and distal liver metastasis in TNBC tumor-bearing nude mice by inactivating the TGF-β1/SMAD3 signaling pathway through the suppression of CCDC150 expression." (PMID 38420580, 2024). "CHI3L1 has the potential to enhance tumor growth and migration by interacting with TGF-β1 and TGFR, which subsequently activates the SMAD2/SMAD3 signaling pathway." (PMID 38177294, 2024). "For the induction of Treg in the tumor microenvironment, exosomal circGSE1 was released from HCC cells and regulated miR-324-5p/TGF-β receptor 1 (TGFBR1)/SMAD family member 3 (SMAD3) axis." (PMID 39273280, 2024). "Tumor volume and weight were increased in mice treated with H460/oe-SMAD3 + Gy or H460/CAFs + Gy, and conversely, H460/oe-SMAD3 + sh-ITGA6 + Gy or H460/CAFs + sh-ITGA6 + Gy led to reduced tumor volume and weight." (PMID 38493128, 2024). "The tumor-suppressive role of TGF-β signaling via the canonical pathway is mediated by Smad2 and Smad3." (PMID 38256080, 2024). "Overall, Smad3-mediated inhibition of GM-CSF production in NK cells significantly impeded the recruitment of DCs and M1 macrophages in LLC tumor, which consequently reduced effector T cells in LLC microenvironment." (PMID 38878186, 2024). "It promotes M2 macrophage polarization to drive the TGFβ/Smad3/COL5A1 signaling pathway, leading to tumor drug resistance." (PMID 38918587, 2024). "As proposed as a tumor suppressor, miR-136-5p functionally interacts with a variety of target genes, such as ROCK1 41, BCL2 42, or SMAD3 43, to interfere with cancer cell invasion and migration." (PMID 38495489, 2024). "The results showed that ANXA5, MMP1, MTR, REN, SCN4A, and SMAD3 were upregulated in HC samples, while HP and ACOX1 were downregulated in tumor tissues." (PMID 38599581, 2024). "Meanwhile, the delivery of such tumor-derived EVs to CD8+ T cells sets SMAD3 and TCF1 transcription factors in motion, consequently leading to the exhaustion of CD8+ T cells and minimizing their anti-tumor function." (PMID 39091989, 2024). "The robust induction of IFNγ suppressed both TGFβ-dependent SMAD3 activation and CCKAR-AKT signaling–mediated collagen expression in the tumor microenvironment." (PMID 39574893, 2024). "The aim of the study was to evaluate promoter methylation of CDKN1, CDKN2A, MYC, Smad3, SP1, and UBC genes in tumor tissue of HNSCC patients." (PMID 38540340, 2024). "IHC staining revealed enhanced Linc00673-V3, Smad3, and LC3B expression in tumor tissues when treated with cisplatin, which is largely attenuated by ASO-Linc00673-V3." (PMID 38527804, 2024).
tumor (continued). "In conclusion, this study indicates that tumor-infiltrating ADSCs promote glycolysis and anoikis resistance in CRC cells and ultimately facilitate peritoneal metastasis via the TGF-β1/SMAD3/ANGPTL4 axis." (PMID 38643448, 2024). "Similar effects were also observed in the LLC tumor, where the accumulation of CD18+ neutrophils was significantly enhanced by Smad3 knockout NK therapy compared with Smad3 wild-type NK therapy." (PMID 38878186, 2024). "INHBA on SPP1+ macrophages is predicted to interact with ACVR1 on tumor cells, targeting downstream genes, including SERPINE1 and SMAD3, which positively regulate cyclin-dependent protein kinase activity." (PMID 38519500, 2024). "Tumor immunity In the tumor microenvironment, TGF-β downregulates the expression of EOMES by binding to SMAD family member 3 (SMAD3)." (PMID 38965548, 2024). "Besides, multivariate Cox regression analysis data indicated that SMAD3 expression (p = 0.005, HR = 1.721, 95% CI 1.180–2.510), tumor stage (p = 0.010, HR = 1.288, 95% CI 1.063–1.561), and age (p = 0.008, HR = 1.026, 95% CI 1.007–1.046) could serve as independent prognostic factors for NSCLC." (PMID 38493128, 2024). "While our preliminary data implicate tumor cell–derived adenosine, TGF-β, and SMAD3 in mediating tumor cell–intrinsic EP4 signaling induced immunosuppression, the precise mechanisms need further investigation." (PMID 39298269, 2024). "Overexpression of SMAD3, SMAD4, and SMAD5 suggests excessive activation of the TGFβ pathway, potentially promoting tumor growth and development." (PMID 39337574, 2024). "CHLD has been found to regulate the expression of proteins Smad3 and Smad7 in the TGF-β1/Smad pathway to inhibit tumor proliferation in tumor-bearing mice with renal cell carcinoma." (PMID 39239653, 2024). "Subsequently, the release of TGF-β1 into the tumor microenvironment by CRC cells activates the SMAD3 pathway in memory CD8+ T cells, ultimately suppressing their anti-tumor activities." (PMID 38971819, 2024). "Here, the authors show that tumor cell-intrinsic ATP6V0A1 drives RABGEF1-dependent cholesterol absorption and thus triggers paracrine TGF-β1/SMAD3 signaling to inactive memory CD8+ T cells in CRC." (PMID 38971819, 2024). "The aim of the study was to investigate the methylation status of CDKN1, CDKN2A, MYC, Smad3, SP1, and UBC genes in tumor tissue (control-normal tissue) in 50 patients (37 men and 13 women) with HPV-negative HNSCC." (PMID 38540340, 2024). "Again, this observation matchedwith the essential role of oncogene phosphorylation to induce tumor progression; examples include the phosphorylation of BRD4, Smad3, and EGFR." (PMID 37106813, 2023). "Subsequent transcriptomic and epigenomic data integration has allowed us to reveal subtype‐specific molecular pathways governed by AP‐1, SMAD3 and RUNX1/RUNX2 transcription factors (TF) in both pd‐GBSCs and bulk tumours." (PMID 37357610, 2023). "Mechanistically, HOOK1 inhibits tumor growth and metastasis via canonical TGF‐β/ALK5/p‐Smad3 and non‐canonical TGF‐β/MEK/ERK/c‐Myc pathway." (PMID 37085921, 2023). "By knocking down SMAD3 in ADC-TAFs similarly increased TGF-β1/SMAD2 activation and reduced their fibrotic phenotype and anti-tumour response to nintedanib." (PMID 37685308, 2023). "Our results confirmed the roles of β‐catenin, SMAD2, and SMAD3 in promoting EMT, and identified the roles of tumor suppressor MYBBP1A, NKRF, and MYPOP in repressing the EMT process." (PMID 37566765, 2023). "Activin A acts as a tumor‐promoting mediator by increasing tumor cell proliferation and by regulating α‐SMA expression in pancreatic stellate cells in a SMAD3‐dependent manner." (PMID 37083240, 2023). "In lung epithelial cells, SMAD3 binds to ATOH8 to form a transcriptional complex that directly represses a series of cell cycle-promoting genes, leading to senescence and tumour suppression in lung epithelial cells." (PMID 37685308, 2023).